INS (insulin)
Diseases named in the same sentence as INS in open-access papers (continued):
Sharing a sentence is not in itself a finding about the gene and the disease.
Insulin resistance (continued). "The enhanced release of insulin under acute exposure to DHA is well documented, and is generally accepted as the principal mechanism of the beneficial effects of DHA on insulin resistance." (PMID 34578953, 2021). "Homeostasis model assessment for insulin resistance index (HOMA-IR) and quantitative insulin sensitivity check index (QUICKI) were also calculated." (PMID 35047137, 2021). "Evidence indicates that TNF-α and IL-1β facilitate insulin resistance development by elevating blood insulin and HDL cholesterol levels 3 and insulin resistance suppresses keratinocyte differentiation, resulting in persistent proliferation." (PMID 33391503, 2021). "SIRT2 is also described as a novel AKT interactor, critical for AKT activation by insulin, and the potential usefulness of SIRT2 activators in the treatment of insulin-resistant metabolic disorders has been discussed." (PMID 33639916, 2021). "Interestingly, insulin levels are higher in diabesity patients than in normal-weight T2D subjects, implying that the islet beta-cell pathology is more severe in the latter group and that peripheral tissue insulin resistance contributes more to the disease phenotype in overweight T2D patients." (PMID 34413662, 2021). "Body mass index (BMI); homeostasis model assessment of insulin resistance index (HOMA-IR); and fasting blood glucose (FBG), glycated hemoglobin (HbA1c), and insulin levels were used as outcome indicators." (PMID 34488728, 2021). "A set of additional outcomes included fasting insulin and homeostatic model assessment of β-cell function (HOMA-β) and insulin resistance (HOMA-IR)." (PMID 34333586, 2021). "Virulent H. pylori strains induce insulin-regulating gastroduodenal hormones by inducing inflammatory factors IL6, CRP, and chronic inflammation, and ultimately increase insulin resistance." (PMID 34922625, 2021). "AMY and FEN treatments significantly reduced the insulin level in the ITT, suggesting these treatments can reduce HFD-induced insulin resistance." (PMID 34406209, 2021). "As expected, the MUO group displayed higher glucose (p < 0.001), HbA1c (p < 0.01), insulin and HOMA-IR levels (p < 0.01), indicating hyperglycaemia and insulin resistance." (PMID 33801145, 2021). "A commonly used indicator that strongly correlates with insulin resistance assessed by HEC is the homeostatic model assessment for insulin resistance (HOMA-IR), calculated based on fasting glucose and insulin levels." (PMID 34132976, 2021). "Curcumin was also reported to improve insulin resistance and glucose tolerance in db/db mice and HFD-fed mice, and also increased insulin levels in db/db mice." (PMID 34970150, 2021). "Fasting glucose (mmol/l) and insulin (mU/l), insulin resistance (HOMA-IR) and first-phase and second-phase insulin release (Stumvoll first and second phase) were assessed at the same time." (PMID 32661292, 2021). "Blood glucose, plasma insulin concentrations, and HOMA-IR index, a surrogate for estimating insulin resistance, were largely similar from 6 to 16 months and were observed to be lower after 19 months of age." (PMID 33876723, 2021). "Extensive studies have monitored insulin levels in PCOS, and it is shown that the frequency of hyperinsulinemia and insulin resistance is high in PCOS." (PMID 33584143, 2021). "To dissect how endothelial insulin and IGF-1 resistance contributes to whole-body insulin sensitivity in the pathological context of diet-induced insulin resistance, we fed mIGFREO and WT littermates a high-fat diet (HFD) for 10 days." (PMID 34420367, 2021). "Despite greater understanding of molecular pathways in insulin signaling and metabolism, there are still numerous knowledge gaps regarding the etiology of IR in several metabolic disturbances such as NAFLD where insulin resistance seems to play crucial role." (PMID 33681089, 2021).
Insulin resistance (continued). "At 22 weeks of age, an oral glucose tolerance test (OGTT) was performed, and using fasting glucose and insulin values, Homeostasis Model Assessment of Insulin Resistance (HOMA-IR) was calculated as a surrogate measure of insulin resistance." (PMID 34359921, 2021). "Targeted mutations to abolish the function TNF-α receptors and expression of TNF-α improved insulin signaling in obese mice, suggesting TNF-α is critical for the development of insulin resistance." (PMID 33716966, 2021). "It demonstrates that ME efficiently increased insulin levels in the HFD group while also preventing β-cell failure and amelioration of insulin resistance." (PMID 34204891, 2021). "VFT significantly correlated with WC, BMI, hip circumflex (HC), obesity index (OI), fat %, fat mass, insulin, TC, LDL-C, insulin, triglyceride (TG), glucose, homeostatic model assessment for insulin resistance (HOMA-IR) and leptin." (PMID 34746061, 2021). "Fasting plasma insulin and homeostatic model of insulin resistance (HOMA-IR) were elevated in AL groups and significantly reduced by the TRF, indicating improved insulin sensitivity." (PMID 33495474, 2021). "Several studies have reported a positive correlation between IGF-I, insulin resistance, and glucose metabolism; IGF-I was found to improve blood sugar control and insulin sensitivity in healthy adults and DM patients." (PMID 34239560, 2021). "Diabetic rats showed a significant decrease in insulin levels and high HOMA-IR compared with the control animals, indicating the development of insulin resistance." (PMID 33748504, 2021). "The results of GTT and ITT show that the HFD group has impaired glucose regulation and reduced insulin hypoglycemic effect, indicating that HFD can induce glucose metabolism disorder and insulin resistance in mice." (PMID 35047504, 2021). "Lean mice treated with obese ATM exosomes showed obvious insulin resistance, whereas obese mice treated with lean ATM exosomes showed improvement of insulin sensitivity." (PMID 34108967, 2021). "Based on experimental studies, up-regulation of TNF-α and IL-6 induces insulin resistance through activation of JNK and MAPK signaling pathways and consequently disrupts insulin signaling pathway leading to insulin resistance." (PMID 34077450, 2021). "Although the metabolism of liver is generally regulated by insulin and glucagon, NALFD is often accompanied by systemic insulin resistance and the insulin resistance is selective, which makes the actual metabolic state hard to predict." (PMID 34526911, 2021). "We also selected a supraphysiological dose of insulin (100 nM), which was based on the majority of previous primary myotube studies from women with PCOS focusing on insulin resistance." (PMID 34707569, 2021). "Insulin resistance has been reported in up to 70% of PCOS women, and insulin sensitivity is reduced by ~40% in PCOS women, independent of obesity; although obesity further impairs insulin metabolism." (PMID 33800490, 2021). "In the context of SD, glucose, insulin, and leptin levels and HOMA-IR2 (homeostatic measure of insulin resistance) index were significantly reduced at the end of the VLCI period in LCC and FMD mice." (PMID 34753921, 2021). "With increased adiposity, the female 3bKO mice displayed significantly impaired insulin sensitivity as shown by mild glucose intolerance in GTT and more severe insulin resistance in ITT tests when compared to fl/fl mice." (PMID 34439754, 2021). "Systemic insulin resistance indicators, including serum fasting blood glucose (FBG), fasting insulin (FINS), Homeostatic Model Assessment for Insulin Resistance (HOMA-IR), and hemoglobin A1 (HbA1), were examined." (PMID 34745386, 2021). "Serum α-syn levels were also inversely correlated with insulin resistance indicators such as body mass index, homeostatic model assessment for IR (HOMA-IR) and immunoreactive insulin." (PMID 34393754, 2021).
Insulin resistance (continued). "The results indicated that the HFD decreased glucose tolerance and insulin sensitivity in mice; notably, PDX supplementation increased glucose tolerance and improved HFD-induced insulin resistance." (PMID 35185543, 2021). "Homeostatic model assessment of insulin resistance (HOMA-IR) is a method used to estimate whole body insulin resistance based on the relationship between plasma glucose and insulin levels." (PMID 33503847, 2021). "Insulin resistance plays a pivotal role in the pathogenesis of PCOS, the direct consequence of which is abnormally elevated insulin levels." (PMID 34122341, 2021). "In the hepatic insulin resistance model, the MAM interface was also a crucial involvement in insulin signaling via inhibiting ER stress and mitochondrial dysfunction." (PMID 34836936, 2021). "Another study showed higher DNA methylation of COL5A1 in the VAT of women with insulin resistance, revealing an epigenetic regulation of COL5A1 and its implication in pathways related to integrin cell interactions and insulin signaling in VAT." (PMID 33803198, 2021). "After insulin resistance induction in experimental cells, followed by further incubation with DPPC and 1-PA-LPC, the insulin-stimulated glucose uptake rate was measured." (PMID 34684619, 2021). "Mechanistically, PA treatment impairs insulin signaling while increasing ceramide levels in hypothalamic neuronal GT1-7 cells, whereas myriocin or SPT2 siRNA counteracts PA-induced insulin resistance in these cells." (PMID 34069652, 2021). "Clinical trials investigating metformin effects on the evaluation of homeostatic models of insulin resistance (HOMA-IR), Ki-67, body mass index (BMI), fasting blood sugar (FBS), and insulin were selected for further analysis." (PMID 33917520, 2021). "An indicator of insulin resistance is increased expression of PTP1B in insulin-sensitive tissues, while lower expression increases, and enhances glucose uptake and insulin signaling." (PMID 33672051, 2021). "After 28 weeks, fastblood sugar, glucose intolerance, insulin concentration, homeostatic model assessments (HOMA) for insulin resistance (IR) and HOMA for beta cells (HOMA beta) from systematic blood were assessed." (PMID 34155870, 2021). "Other substitute methods were created, such as the Homeostases Model Assessment-Insulin Resistance (HOMA-IR) index, calculated based on fasting glucose and insulin levels, which also has limitations, including the determination of insulin." (PMID 34591406, 2021). "Surrogates for insulin resistance (i.e. HOMA-IR and Matsuda Index) were also calculated, using glucose and insulin concentrations before and after OGTT." (PMID 33438144, 2021). "The primary outcomes are changes in the homeostatic model assessment of insulin resistance (HOMA-IR) and improvements in the oral glucose tolerance test (OGTT) and insulin-releasing test (INS)." (PMID 34743745, 2021). "It was reported that OGT suppressed Insig-1, a negative regulator of lipid synthesis, and induced insulin resistance and dyslipidemia via PIP-dependent insulin signal disturbances." (PMID 35003298, 2021). "Using fasting blood glucose and insulin, we also calculated HOMA-IR as a measure of insulin resistance." (PMID 34204316, 2021). "Animals fed a fructose diet for six months had significantly higher fasting glucose, insulin, HOMA-insulin resistance (IR), and triglyceride levels than the control group (p < 0.05)." (PMID 34836340, 2021). "The AEUG group showed higher values of low-density lipoprotein cholesterol (LDLc) and homeostatic model assessment index-insulin resistance (HOMA-IR) than controls, and higher values of insulin than the other two groups." (PMID 34993223, 2021). "A parallel HOMA-IR assessment indicated that the HFD mice exhibited impaired insulin sensitivity, and MLB supplementation reduced their HFD-induced insulin resistance." (PMID 35010979, 2021).
Insulin resistance (continued). "Our results showed that berberine remarkably lower fasting blood insulin, improve HOMA-IR, and decrease BMI, which demonstrated the advantages of berberine on improving insulin resistance." (PMID 34956436, 2021). "Glucose and insulin as well as the resulting HOMA-IR index, a measure of insulin resistance, were significantly increased in miR-146a−/− mice on an HFD." (PMID 33206203, 2021). "Continuous infusions of acylated ghrelin in healthy subjects and hypopituitary patients for 300 min acutely induced insulin resistance, increased lipolysis, and serum NEFA levels and suppressed insulin-stimulated glucose disposal." (PMID 33419065, 2021). "Diabetic rats exhibited remarkable elevated concentrations of fasting blood glucose, HbA1c with increased insulin resistance, as indicated by the high HOMA-IR levels and decrease in the insulin level due to dysfunction in β-cells." (PMID 33748504, 2021). "However, in this study, the expression of fat Tnfα was not changed by maternal SE, in line with HOMA index ruling out the involvement of insulin resistance, suggesting insufficient insulin production may be the major driver of glucose metabolism disorder in the offspring with in-utero SE exposure." (PMID 34276421, 2021). "In improving insulin resistance, it is reported that BBR increase insulin sensitivity after 5 weeks administration in dietary obese rats and reduce HOMA-IR by 48%." (PMID 34630099, 2021). "After weight loss, a significant improvement in BMI, waist circumference, insulin, fasting blood glucose and HOMA-IR (homeostasis model assessment of insulin resistance) was observed." (PMID 33686615, 2021). "GIP is known to inspect insulin levels in adipocytes and the GIP-R to GLP-1R ratio has been reported to be related to insulin resistance." (PMID 33802091, 2021). "On the other hand, fasting plasma insulin (FPI) and the Homeostatic Model Assessment for Insulin Resistance (HOMA-IR) differed considerably among the three groups, with the highest levels observed in obese T2D participants." (PMID 35050217, 2021). "A study investigated the effect of “dietary approaches to stop hypertension” (DASH) on insulin resistance in the GDM which showed the improvement of fasting blood glucose and serum insulin." (PMID 33663466, 2021). "M1 macrophages induce an inflammatory and insulin resistance state through the inhibition of insulin signaling, indirectly produced by TNF-α, IL-6, and IL-1β, while M2 macrophages protect against insulin resistance by an IL-10-dependent mechanism." (PMID 34944461, 2021). "TNF induced insulin resistance in adipocytes by inhibiting insulin-induced IRS1 tyrosine phosphorylation and insulin-induced glucose uptake and played a role in angiogenesis by inducing VEGF production synergistically with IL-1B and IL-6." (PMID 34306139, 2021). "ROS impair insulin signalling pathway, activate JNK and deteriorate phosphorylation of IRS contributing to the development of hepatic insulin resistance." (PMID 34034759, 2021). "Then, we performed a series of experiments, such as fasting/refeeding assay, glucose/insulin tolerance test, and acute insulin response assay, to analyze the in vivo role of hepatic SND1 in the HFD-induced insulin resistance." (PMID 34608846, 2021). "Elevated fasting insulin levels are a common measure of insulin resistance, and decreased HDL cholesterol and elevated triglyceride levels are also hallmarks in insulin resistant individuals." (PMID 34143812, 2021). "Gluconeogenic genes typically suppressed by insulin were upregulated in the muscle and other metabolic tissues of TMAO supplemented mice, indicating a link between TMAO and insulin resistance." (PMID 34445033, 2021). "Fasting Insulin, Insulin-to-glucose ratio, Homeostasis Model Assessment Insulin (HOMA), Homeostasis Model Assessment-Insulin Resistance (HOMA-IR), HOMA-B and QUICKI were all reported as significantly increased by several studies (n = 752)." (PMID 34635186, 2021).
Insulin resistance (continued). "Thus, the potential positive effect of cyclosporine on glycemic control in the cats with DM and presumed CP in our study may be either indirect by reducing pancreatic inflammation and insulin resistance or direct by preserving β-cell function and insulin secretion." (PMID 34680012, 2021). "One potential mechanism is that elevated BCAAs levels lead to activation of the mTOR/S6K1 pathway and serine phosphorylation of IRS1, contributing to inhibition of insulin-induced PI3K activation and insulin resistance." (PMID 34419103, 2021). "The results indicated that fenofibrate treatment reduced homeostasis model assessment-insulin resistance (HOMA-IR) values and increased homeostasis model assessment-insulin sensitivity index (HOMA-ISI)." (PMID 35126113, 2021). "Coherently with such fact, recent studies addressed ERK1 knockout mice having a weight gain and insulin resistance, while ERK2 liver-specific knockout mice also developed hepatic steatosis, glucose intolerance, and diminished insulin sensitivity." (PMID 34361079, 2021). "The ability of apoA-I to reduce insulin resistance in pregnancy were not, however, confirmed in a recent small, retrospective cross-sectional study of women with gestational diabetes, where serum apoA-I levels were found not to be associated with insulin sensitivity." (PMID 33918571, 2021). "Regarding non‐cytosolic PLA2s, iPLA2ζ was shown to downregulate insulin signaling and GLUT4 translocation leading to insulin resistance in mouse skeletal muscle." (PMID 33433056, 2021). "Still, the average fasting plasma insulin (FPI) and the insulin resistance index, HOMA-IR, were significantly lower in the control group compared to obese subjects." (PMID 34440238, 2021). "Sunitinib led to the decreased insulin sensitivity as determined by insulin tolerance test (ITT) and glucose tolerance test (GTT), reflecting insulin resistance occurred in sunitinib-treated rats." (PMID 33841146, 2021). "In addition, the low-grade of inflammation associated with the situation of insulin resistance results in an enhanced production and secretion of pro-inflammatory mediators (tumor necrosis factor [TNF]-α, interleukin [IL]-6, etc.)that in turn inhibits the insulin signaling pathway." (PMID 34208379, 2021). "Glucose, HbA1c, triglyceride, low density cholesterol (LDL), leptin, and Homeostatic Model Assessment for insulin resistance (HOMA-IR) levels increased and insulin and HOMA-β levels decreased in the diabetic rats compared to the healthy control group." (PMID 33641315, 2021). "In contrast, treatment of the mice with PW (300 mg/kg) resulted in significant reductions in the insulin level and the HOMA-IR index, indicating improvements in hyperinsulinemia and insulin resistance were induced by the HFD." (PMID 34451554, 2021). "That is to say, insulin acts on insulin receptor to activate PI3K/Akt pathway, and then the expression of ANGPTL8 increases; in insulin resistance, PI3K/Akt pathway was damaged and ANGPTL8 expression was downregulated." (PMID 34582711, 2021). "The alga supplementation also lowered plasma glucose, insulin and the homeostatic model assessment for insulin resistance (HOMA-IR) index, meaning that insulin resistance was reduced." (PMID 34208211, 2021). "Insulin levels were significantly higher in women with PCOS, as well as insulin resistance in both studies." (PMID 34239559, 2021). "The homeostasis model assessment for insulin resistance (HOMA-IR), HOMA of percentage β-cell function (HOMA-β), quantitative insulin sensitivity check index (QUICKI), and triglyceride and glucose index (TyG-index) were measured and recorded as IR surrogates." (PMID 34073195, 2021). "Insulin resistance accelerated the development of PND, intranasal insulin treatment prevents anesthesia-induced cognitive impairments." (PMID 34248489, 2021). "Fasting glucose and insulin serum levels were also measured and HOMA-IR (insulin resistance index) was calculated." (PMID 34049596, 2021).